HMGA2 (high mobility group AT-hook 2)
Diseases named in the same sentence as HMGA2 in open-access papers (continued):
Sharing a sentence is not in itself a finding about the gene and the disease.
leiomyoma (51 papers, 2010 to 2025). A well-circumscribed benign smooth muscle neoplasm characterized by the presence of spindle cells with cigar-shaped nuclei, interlacing fascicles, and a whorled pattern. "One recent study suggested the leading role of HMGA2 aberrations in uterine leiomyoma tumorigenesis, which is overexpressed even in leiomyomas with MED12 mutation." (PMID 37466765, 2024). "HMGA2 rearrangements have been associated with larger tumor size and a smaller number of tumors compared with leiomyomas with a MED12 mutation." (PMID 35822448, 2023). "Kurita’s group has recently reported that subtypes of leiomyoma with either MED12 mutations or HMGA2 overexpression required progesterone and 17β-estradiol to stimulate tumor growth." (PMID 35203298, 2022). "MED12 mutations were the most common alterations in conventional and mitotically active leiomyomas and leiomyosarcomas, while leiomyomas with bizarre nuclei were most often FH deficient and cellular tumors showed frequent HMGA2 overexpression." (PMID 28592321, 2017). "However, none of the samples with an HMGA1 or PLAG1 rearrangement in this study harbored an alteration in a well‐established leiomyoma driver gene and all displayed expression features associated with leiomyomas of the HMGA2‐subtype." (PMID 35822448, 2023). "Additionally, the overexpression of HMGA2 in leiomyomas was shown to be associated with increased vasculature density, demonstrated by the increased expression of angiogenic factors and receptors, such as VEGFA, EGF, bFGF, TGFα, VEGFR1, and VEGFR2, which likely contribute to tumour growth." (PMID 35805007, 2022). "Recently, it has been suggested that leiomyomas with bizarre nuclei can be divided into two subtypes based primarily on nuclear features; some tumors show significantly higher rates of HMGA2 immunoreactivity and frequent MED12 mutations and the others may occasionally be related to FH mutations." (PMID 28592321, 2017). "In karyotypically abnormal leiomyomas, cytogenetic aberrations commonly include deletions in 7q, trisomy of chromosome 12, and various translocations between chromosomes 12 and 14 involving the high mobility group AT-hook 2 (HMGA2) gene at 12q15, which encodes a transcriptional regulator." (PMID 22428002, 2012). "Leiomyoma-associated driver alterations in MED12, HMGA2, and FH have been reported in up to one-third of uterine leiomyosarcomas." (PMID 41162745, 2025). "In agreement with our data, HMGA2 expression had previously been described in 9.5–96.2% of leiomyomas and in 54% of 13 bronchial lipomas." (PMID 40518465, 2025). "HMGA2 serves as a driver of tumor metastasis, and its overexpression is an early event in leiomyoma development, which plays a pivotal role in the pathogenesis of IVL." (PMID 40276735, 2025). "Three well-established driver alterations in leiomyomas are MED12 mutations, chromosomal rearrangements leading to HMGA2 overexpression, and biallelic mutations resulting in FH-deficiency, which together account for 80–90% of the tumors." (PMID 41162745, 2025). "The third theory suggests genetic tendencies toward leiomyoma development implicated through molecular alterations in MED12 and HMGA2 genes." (PMID 40115706, 2025). "Another study comparing uterine leiomyoma and leiomyosarcoma found that a small percentage (3 out of 56) of leiomyoma cases showed a RAD51B fusion (with HMGA2, NCOR2, and NUDT3), and one of these cases with RAD51B::NUDT3 fusion is reported here in detail." (PMID 37466765, 2024). "Uterine leiomyoma with HMGA2 overexpression is the most common subtype in cellular and second most common category of usual leiomyoma." (PMID 37466765, 2024). "A hotspot mutation in MED12 or a chromosomal rearrangement of HMGA2 that leads to a significant HMGA2 overexpression account for 80%–90% of all leiomyomas." (PMID 35822448, 2023).
leiomyoma (continued). "The accuracy of diagnosis is facilitated by the absence or extremely low level of HMGA2 expression in normal myometrium, although there are reports of the possibility of moderate HMGA2 expression in MED12-dependent fibroids." (PMID 37987267, 2023). "The triple‐negative samples were analyzed together with a previously published dataset of 15 HMGA2 overexpressing leiomyomas that served as positive controls." (PMID 35822448, 2023). "To conclude, we have here confirmed that leiomyomas with an HMGA2, HMGA1, or PLAG1 rearrangement share multiple molecular features, including similar gene expression patterns and shared translocation partners." (PMID 35822448, 2023). "In a few leiomyomas, we detected HMGA2 or HMGA1 to be combined with a candidate partner gene in opposite directions." (PMID 35822448, 2023). "This suggests that these tumors form a distinct leiomyoma subtype, expanding the HMGA2‐subtype to an HMGA‐subtype." (PMID 35822448, 2023). "In this case, the trials should be carried out on a group of patients with HMGA2-dependent leiomyoma." (PMID 37987267, 2023). "In line with the 3′RNA‐sequencing results, the structural variant analysis detected an HMGA2 rearrangement in eight leiomyomas, an HMGA1 rearrangement in four leiomyomas, and a PLAG1 rearrangement in four leiomyomas." (PMID 35822448, 2023). "Cell line studies have already demonstrated that angiogenic factors play a role in HMGA2‐mediated tumorigenesis, indicating therapeutic potential of angiogenesis inhibitors in HMGA2‐positive leiomyomas." (PMID 35822448, 2023). "Recently, C-terminal Src kinase (CSK2) and high mobility group AT-hook 2 (HMGA2) were highlighted as key players in leiomyomas tumorigenesis." (PMID 35805007, 2022). "In leiomyomas, HMGA2 overexpression up-regulated IGF2BP2 and pAKT, which played an important role in the IGF2BP2-mediated pAKT activity in angiogenesis." (PMID 36281789, 2022). "The driver mutations critical to leiomyoma development and progression include MED12 (mediator complex subunit 12), HMGA2 (high mobility group AT-hook 2), FH (fumarate hydratase), and COL4A5/6 (collagen type IV, alpha 5, and alpha 6)." (PMID 35641855, 2022). "Another important finding is that leiomyomas with HMGA2 overexpression mainly consist of smooth muscle cells." (PMID 35203298, 2022). "Mutations in myometrial cells that affect the expression of the HMGA2 gene are also reported, leading to the formation of leiomyoma-like tissue in xenograft models." (PMID 34445194, 2021). "Rearrangements in the 12q14–15 region in fibroids are reported to increase expression of the HMGA2 gene." (PMID 34445194, 2021). "Principal component analysis using the 3′RNA sequencing data revealed that the 49 (44 leiomyomas + 5 myometrium) samples and 11 technical replicates grouped according to the predetermined mutation status of MED12, HMGA2, and FH." (PMID 33352722, 2020). "We and others have previously shown that MED12, HMGA2, and FH aberrations result in distinct global gene expression patterns, suggesting that leiomyomas can be classified by gene expression profiling." (PMID 33352722, 2020). "In particular, suppression of the signaling pathway associated with the activation of the insulin-like growth factor IGF2BP2 gene is promising for the treatment of fibroids with overexpression of the HMGA2 gene." (PMID 31817606, 2019). "Although the number of leiomyomas of deep soft tissue so far studied is still very low, the findings with regard to 12q13∼15 aberrations/expression of HMGA2 seem to be similar to those made in uterine leiomyomas." (PMID 28591699, 2017). "In the leiomyomas with 12q rearrangements, both HMGA2 and PLAG1 were expressed whereas in the tumors with 8q aberrations, only PLAG1 was expressed." (PMID 28591699, 2017).
leiomyoma (continued). "Prolactin was one of the most up-regulated genes in leiomyomas with HMGA2 rearrangements, MED12 mutations and COL4A5-COL4A6 deletion supporting its role as a mitogenic autocrine growth factor in human leiomyoma tumorigenesis." (PMID 28930160, 2017). "In leiomyomas and leiomyosarcomas, let-7c shows an inverse correlation with its target mRNA high mobility group AT-hook 2 (HMGA2)." (PMID 23830214, 2013). "Among many dysregulated microRNAs and target genes in leiomyomas, correlation of HMGA2 and the let-7 family has been well characterized and shown as biologically significant for leiomyoma growth." (PMID 20808773, 2010). "Significant upregulation of PLAG1 was described in HMGA2 subtype of leiomyoma." (PMID 37466765, 2024). "Fibroids are frequently associated with genetic alterations affecting mediator complex subunit 12 (MED12), fumarate hydratase (FH), high mobility group AT-hook 2 (HMGA2) and collagen, type IV alpha 5 and alpha 6 (COL4A5-COL4A6)." (PMID 37113812, 2023). "In addition to rearrangements of HMGA1, HMGA2, and PLAG1, we identified biallelic loss of DEPDC5 in one leiomyoma with an HMGA2 rearrangement and in another leiomyoma with an HMGA1 rearrangement." (PMID 35822448, 2023). "Inducing common mutations observed in fibroids in CRIP1+/PECAM1- myometrium cells, such as MED12 (exon 2, 131 G > A, G44D) or overexpression of HMGA2, could provide insight into fibroid etiology and models to evaluate alternative therapeutics." (PMID 37400623, 2023). "Although some studies have indicated that HMGA1 overexpressing leiomyomas result in a distinct expression profile, our observations are compatible with a recent RNA‐sequencing study on 276 leiomyomas in which most HMGA2 and HMGA1 overexpressing leiomyomas clustered together." (PMID 35822448, 2023). "A few leiomyomas displayed breakpoints downstream of HMGA2 and HMGA1, suggesting that also downstream rearrangements could result in their upregulation." (PMID 35822448, 2023). "Interestingly, we identified a subset of tumors to display expression features typically seen in leiomyomas with an HMGA2 rearrangement, including PLAG1 overexpression." (PMID 35822448, 2023). "MED12 mutant fibroids had 4.4 times higher odds of shrinking in response to ulipristal acetate treatment as compared to HMGA2 driven fibroids (95% confidence interval 1.37–13.9; P = 0.013), and in a multivariate analysis molecular subclassification was an independent predictive factor." (PMID 36048862, 2023). "Our results indicate that the frequency of HMGA2‐positive leiomyomas may have been underestimated in previous studies where only immunohistochemistry has been used." (PMID 35822448, 2023). "The HMGA2 (high mobility group AT-hook 2) gene is overexpressed in 65% of these types of tumors and mutations in a transcriptional regulator complex subunit 12 (MED12) are demonstrated in 70% of fibroids." (PMID 34442017, 2021). "Not surprisingly, HMGA2 plays a key role in cell proliferation and has been associated with various cancer types including colorectal, lung, gastric, colon, leiomyoma, and oesophageal squamous cell carcinoma." (PMID 34440306, 2021). "As HMGA2 is among the key driver genes in leiomyomas, we tested whether H19 regulates its expression in leiomyoma cells." (PMID 31089260, 2019). "Thus, we concluded that in primary leiomyoma cells H19 promotes HMGA2 expression at the translational level by reducing the bioavailability of let-7." (PMID 31089260, 2019). "In a recent study, MED12 mutations were also found in 34% of leiomyoma/leiomyomatosis in pelvic/retroperitoneal sites but there was no information about the status of HMGA2 and HMGA1." (PMID 25621995, 2015). "Both genes, let-7c and HMGA2, are expressed in association with size of leiomyomas, while in PTSMT, irrespective of the size, let-7c was almost absent." (PMID 23830214, 2013). "Moreover, overexpression of HMGA1 and/or HMGA2 is in leiomyomas common finding." (PMID 37466765, 2024).
leiomyoma (continued). "Thus, the growth of smooth muscle cells is important in HMGA2 overexpressing leiomyoma." (PMID 35203298, 2022). "In addition, we identified AKR1B10 expression in nine leiomyomas with no indication of FH-deficiency or alterations affecting MED12 or HMGA2." (PMID 36068196, 2022). "HMGA2 overexpression is the second major genetic alteration accounting for approximately 10% in uterine leiomyoma cases, but its expression is limited in the leiomyoma without underlying MED12 mutations." (PMID 35203298, 2022). "Although alterations in MED12 and HMGA2 seem to be mutually exclusive, whether these genetic alterations induce the transformation of myometrial stem cells or maintain already existing leiomyoma stem-progenitor cells remains unclear." (PMID 34445194, 2021). "Fibroid tumors stratify into four main subtypes that are dependent on the mutational status of mediator of transcription subunit 12 (MED12), fumarate hydratase (FH), high mobility group AT-hook 2 (HMGA2) translocations, and collagen (COL4A5-COL4A6) gene deletions." (PMID 32094355, 2020). "Notably, genome-wide analyses of fibroids harboring different genetic alterations have revealed fibroid subtypes with distinct driver pathway genes, and MED12 and HMGA2 have been found to be the most common driver genes that together account for nearly 90% of all fibroids." (PMID 31089260, 2019). "Approximately 30%–40% of fibroids have been reported as having karyotypic abnormalities, with the most commonly reported being translocations at chromosome regions of 12q15 and 6q21, leading to overexpression of the high mobility group AT-hook genes, HMGA2 and HMGA1, respectively." (PMID 31851934, 2019). "Early cytogenetic studies on leiomyomas and other benign mesenchymal tumors identified RAD51B as the most common translocation partner for HMGA2, often in the form of a balanced translocation." (PMID 35822448, 2023). "The samples were analyzed together with a previously published dataset of 44 leiomyomas with a driver alteration in MED12, HMGA2, or FH as well as five myometrium samples." (PMID 35822448, 2023). "We identified chromosomal rearrangements targeting either HMGA2, HMGA1, or PLAG1 in all 16 tumors, demonstrating that it is possible to detect chromosomal driver alterations in archival leiomyoma specimens as old as 18 years." (PMID 35822448, 2023). "One of these clusters consisted of 16 leiomyomas that showed high expression of HMGA1 and the other consisted of 12 leiomyomas that displayed exceptionally high expression of PLAG1, but low expression of both HMGA1 and HMGA2." (PMID 35822448, 2023). "Indeed, 80–90% of leiomyomas harbor one of three genetic changes: a hotspot mutation in mediator complex subunit 12 (MED12), a chromosomal aberration resulting in upregulation of high mobility group AT-hook 2 (HMGA2), or biallelic loss of fumarate hydratase (FH)." (PMID 36068196, 2022). "HMGA2 and CD24 showed broader expression patterns and higher signal intensity in leiomyoma than in myometrial cells." (PMID 35884847, 2022). "For example, leiomyomas of the MED12 subtype are typically more numerous, smaller in size, and subserosal; leiomyomas of the HMGA2 subtype are larger, isolated, and have a high vasculature density making them potentially sensitive to angiogenesis inhibitors." (PMID 33352722, 2020). "Indeed, 80−90% of leiomyomas harbor one of three genetic changes: a hotspot mutation in mediator complex subunit 12 (MED12), a chromosomal aberration resulting in significant overexpression of high mobility group AT-hook 2 (HMGA2), or biallelic loss of fumarate hydratase (FH)." (PMID 33352722, 2020). "All leiomyomas showed dysregulation of 70 metabolites, and distinct metabolomics profiles were seen for different genetic subtypes of leiomyomas (i.e.; FH, MED12, HMGA2)." (PMID 33371433, 2020).
leiomyoma (continued). "In this report we show that H19 expression is significantly increased in fibroids as compared with normal myometrium, and that H19 functions to promote leiomyoma cell proliferation and expression of MED12, HMGA2, TET3, and ECM-remodeling genes." (PMID 31089260, 2019). "Leiomyosarcomas did not cluster together based on the presence of the established leiomyoma-associated driver mutations, unlike leiomyomas, which clustered according to the underlying MED12, HMGA2, or FH alteration." (PMID 41162745, 2025). "3′RNA‐sequencing of 111 leiomyomas that were previously classified as triple‐negative revealed high HMGA1 or HMGA2 expression in a subset of leiomyomas." (PMID 35822448, 2023). "Here, we performed 3′RNA‐sequencing with 111 leiomyomas that had been previously classified as negative for a MED12 mutation, HMGA2 overexpression, and FH‐deficiency by Sanger sequencing or immunohistochemistry." (PMID 35822448, 2023). "The involvement of many proteins such as FN1, COL1A1, BMP7, CCND1, EZH2, HMGA2, AhR, and E2F1 shown in the protein–protein interaction networks are well known in leiomyoma pathogenesis; others, such as SOX2, REN, PPARG, ABCB1, and NR3C1 are novel and require further investigation." (PMID 36835153, 2023). "WGS identified an HMGA2 rearrangement in all eight tumors that displayed HMGA2 overexpression by 3′RNA‐sequencing, including the four leiomyomas without strong HMGA2 protein expression." (PMID 35822448, 2023). "Leiomyomas with an intragenic breakpoint in HMGA2 were also not predicted to form fusion genes based on the orientation of some of the rearrangement partners." (PMID 35822448, 2023). "These tumors were also negative for MED12 and HMGA2 defects, as well as for mutations in genes encoding for proteins of the SRCAP complex, another recently discovered leiomyoma subtype." (PMID 36068196, 2022). "As expected, we detected significant upregulation of PLAG1 in leiomyomas of the HMGA2 and FH subtypes, but not in leiomyomas of the MED12 subtype." (PMID 33352722, 2020). "Overexpression of HMGA2, a gene normally not highly expressed in normal myometrium, is the second most common phenomenon known to occur in fibroids." (PMID 31851934, 2019). "None of the tumors displayed simultaneously more than one leiomyoma driver alteration, indicating that MED12 mutations, HMGA2 overexpression, and biallelic FH inactivation are mutually exclusive." (PMID 28592321, 2017). "The most prevalent alterations in conventional ULs were only rarely observed in leiomyomas with bizarre nuclei: MED12 mutations were identified in three out of 18 tumors (16.7%) and none displayed HMGA2 overexpression." (PMID 28592321, 2017). "HMGA2 is overexpressed in leiomyomas both with and without chromosome rearrangement of 12q14–15 suggesting a general role of this gene in leiomyoma development." (PMID 25621995, 2015). "RAD51B may be a fusion partner of HMGA2 and HMGA1 but can occur in fusion with other genes including NUDT3 and seems to be a potential driver event in these tumors mutually exclusive with other driver aberrations defining molecular leiomyoma subtypes." (PMID 37466765, 2024). "The literature suggests that HMGA2 protein expression along with the translocation of t12;14 q15;q24 is more common in patients with IVL, which may play an important role in allowing the invasion of leiomyomas into the vascular system." (PMID 38085353, 2024). "Unlike HMGA2 rearrangements, HMGA1 and PLAG1 rearrangements are rare in leiomyomas and may co‐occur with MED12 mutations, suggesting that they are secondary events related to tumor progression." (PMID 35822448, 2023). "In addition, although the great majority of leiomyomas can be explained by defects in MED12, HMGA2, or FH, there is a small subset of leiomyomas where the driver alteration is unknown." (PMID 33352722, 2020).